DNMT3B (DNA methyltransferase 3 beta)
Diseases named in the same sentence as DNMT3B in open-access papers (continued):
Sharing a sentence is not in itself a finding about the gene and the disease.
colon carcinoma (continued). "DNMT1 and DNMT3B modulate distinct polycomb-mediated histone modifications in colon cancer." (PMID 24822169, 2014). "Recent studies suggest that an interaction between DNMT1 and DNMT3B may be vital for the maintenance of patterns of DNA methylation in human colon-cancer cells, particularly in repeat regions and imprinted genes." (PMID 24822169, 2014). "The DNA methyltransferase DNMT3B maintains hematopoietic and neural stem cells, has been shown to promote in vivo tumorigenesis of colon cancer by transcriptional silencing of tumor suppressor genes, and is also involved in therapy resistance by inducing cell cycle arrest." (PMID 24098529, 2013). "It was reported that HOXB13 gene was a target of DNMT3b in colon cancer cells." (PMID 22808286, 2012). "Using RNA interference we reduced DNMT3B protein levels in colon cancer cell lines." (PMID 22563479, 2012). "In HCT116 colon cancer cells, disruption of DNMT1 and DNMT3B decreases the 5-mC concentration by 95% and delays cell proliferation." (PMID 37742010, 2023). "Therefore, we identified that VIRMA and DNMT3B could play vital roles in colon cancer." (PMID 37421455, 2023). "They generated double knockout of DNMT1 and DNMT3B, which eliminated most of DNA methylation in HCT116, a colon cancer cell line." (PMID 31497535, 2019). "In colon cancer cells, HOXB13, as a target of DNMT3b, was methylated at an upstream CpG island, and functioned as a tumor suppressor in primary colorectal tumors." (PMID 22808286, 2012). "Knowing that CpG hypomethylation is involved in BORIS activation, we compared BORIS expression in the HCT116 colon cancer cell line to HCT116 cells treated with 5aza-dC, and to HCT116 bearing a double knockout (DKO) of DNMT3b and DNMT1." (PMID 21079786, 2010). "Moreover, in colon cancer cells, the epigenetic silencing of CDKN2A and MLH1 genes was also correlated with enhanced levels of DNMT1 and DNMT3B." (PMID 38504782, 2024). "Finally, to identify the key biological function of m6A/m5C/m1A regulators in colon cancer, we performed immunohistochemical staining and RT-qPCR to screen two key biomarkers (VIRMA and DNMT3B)." (PMID 37421455, 2023). "We took advantage of the development of an isogenic cell line obtained from the human colon cancer cell line HCT-116, where the DNA methyltransferases 1 (DNMT1) and 3B (DNMT3B) genes have been genetically disrupted by homologous recombination (double knockout cells, DKO)." (PMID 30018746, 2018). "By endogenous co-immunoprecipitation, we found KDM1A to bind DNMT1 and DNMT3B in two different cancer cell lines: when we immunoprecipitated endogenous KDM1A from whole-cell extracts of the colon cancer cell line HCT116, we detected DNMT1 and DNMT3B by western blotting." (PMID 27449289, 2016). "For instance, the knockout of DNMT1 or DNMT3B alone in the human colon cancer cell line HCT116 does not impact DNA methylation, while their concomitant invalidation induces profound hypomethylation leading to a minimal methylation footprint on DNA." (PMID 25948775, 2015). "recently reported that DNMT3B depletion in human colon cancer cells induced cell growth arrest and apoptosis without changes in their DNA methylation pattern." (PMID 25948775, 2015). "In summary, genome-wide methylation analyses demonstrate that DNMT3B does not play a significant role in maintaining methylation patterns of HCT-116 colon cancer cells." (PMID 22563479, 2012). "Previous reports have shown that silencing of DNMT3b does not appear to affect DNA methylation of any of the genes in cells derived from colon cancer." (PMID 18798999, 2008). "We profiled with 850k arrays three replicates of the well-characterized HCT116 human colon cancer wild type (WT) cell line and of its double knock-out (DKO) derivative, in which DNA methylation is strongly reduced because of deletion of the DNMT1 and DNMT3B DNA methyltransferase genes." (PMID 36354000, 2022).
colon carcinoma (continued). "Even the complete absence of DNMT3B in 3BKO cells did not affect the hypermethylation phenotype of HCT-116 colon cancer cells, indicating that the observed antiproliferative effects of DNMT3B depletion are not caused by DNA demethylation of putative DNMT3B target genes." (PMID 22563479, 2012). "However, our results clearly indicate that the CpG island methylator phenotype (CIMP) which has been established using the same array-based methods before is not affected by depletion of DNMT3B in established colon cancer cell lines in vitro." (PMID 22563479, 2012). "It should be noted however that PC3 cells contain moderate levels of DNMT1 and DNMT3a which are not affected when DNMT3b is silenced (data not shown); like PC3, colon cancer cells also express DNMT1 and DNMT3a." (PMID 18798999, 2008). "Additionally, drug-induced demethylation was compared to methylation patterns of isogenic colon cancer cells lacking both DNA methyltransferase 1 (DNMT1) and DNMT3B." (PMID 21408221, 2011). "We compared HCT116 colon cancer cells and HCT116 double knock out (DKO) cells that have been genetically disrupted to give severe haplo-insufficiency of DNMT1, and complete absence of DNMT3B, enzymes for DNA methylation maintenance and de novo DNA methylation, respectively." (PMID 24162015, 2013).
Immunodeficiency (54 papers, 2006 to 2026). Failure of the immune system to protect the body adequately from infection, due to the absence or insufficiency of some component process or substance. "In humans, biallelic hypomorphic mutations in the DNMT3B gene cause immunodeficiency, centromeric instability, facial anomalies type 1 (ICF1) syndrome (OMIM #242860)." (PMID 38136588, 2023). "This study used DNA methyltransferase 3b (DNMT3b) knockout cells and the functional loss of DNMT3b mutation in immunodeficiency-centromeric instability-facial anomalies syndrome (ICF) cells to understand how DNMT3b dysfunction causes genome instability." (PMID 35688824, 2022). "Loss-of-function mutation in DNMT3b is specifically found in a rare human genetic disorder, immunodeficiency-centromeric instability-facial anomalies (type-1 ICF) syndrome." (PMID 35688824, 2022). "Mutations in the human DNMT3B gene result in ICF (immunodeficiency, centromeric region instability, and facial anomalies syndrome)." (PMID 34586646, 2021). "HSCT replaces all hematopoietic cells carrying the DNMT3B mutation and can thereby cure the immunodeficiency in ICF patients." (PMID 28713390, 2017). "This is an important question as recently mutations in LSH were found in a subset of patients with ICF (Immunodeficiency, Centromeric instability and Facial anomalies) syndrome, a human disease most commonly associated with congenital mutations in DNMT3B." (PMID 27179028, 2016). "DNMT-3B gene mutations have been shown to cause the immunodeficiency–centromeric instability–facial anomalies syndrome, which is characterized by hypomethylation of pericentromeric repeats." (PMID 26103880, 2015). "In fact, inactivation of Dnmt3b results in embryonic lethality, Dnmt3a knockout mice die shortly after birth and more, mutations in the human DNMT3b gene are connected with ICF (Immunodeficiency, Centromere instability and Facial anomalies) syndrome." (PMID 21860617, 2012). "Expression profiling of ICF patients identified over 30 genes specific for lymphocyte signalling that are deregulated in this immune system disorder as a result of a DNMT3b mutation." (PMID 19506729, 2008). "Similarly, hypomorphic mutation in DNMT3B was associated with immunodeficiency, centromere instability, facial anomalies syndrome, characterized by facial abnormalities and mental retardation." (PMID 39678047, 2024). "Germline mutations in DNMT3B cause immunodeficiency, centromeric instability and facial anomalies (ICF) syndrome and chromosome instability, and single nucleotide polymorphisms in DNMT3B are associated with an increased risk of several cancers including breast and lung adenocarcinoma." (PMID 36979633, 2023). "Furthermore, many pathogenic allelic variants in DNMT3B have been identified, all of which were associated with the immunodeficiency-centromeric instability-facial anomalies syndrome 1 (ICF1) (OMIM 242,860)." (PMID 34758722, 2021). "Moreover, the loss of DNMT3B, mutations in which cause immunodeficiency-centromeric instability-facial anomalies syndrome, appears not to contribute to the present phenotype." (PMID 23476833, 2013). "Immunodeficiency, centromeric instability, facial anomalies (ICF) syndrome is a rare autosomal recessive disorder that is caused by mutations in either DNMT3B, ZBTB24, CDCA7, HELLS, or yet unidentified gene(s)." (PMID 33082427, 2020). "Constitutional mutations in the catalytic domain of DNMT3B have been described and are responsible for hereditary syndrome characterized by ICF (immunodeficiency, instability of the centromeric region of chromosomes and facial abnormalities) in humans." (PMID 23251566, 2012). "Immunodeficiency, centromeric instability, and facial anomalies syndrome (ICF) is a rare genetic defect that is inherited in an autosomal recessive manner, and the pathogenic genes include DNMT3B, ZBTB24, CDCA7, and HELLS." (PMID 39958354, 2025).
Immunodeficiency (continued). "To explore the role of DNMT3B in mediating de novo DNA methylation at imprinted DMRs, we utilized iPSCs generated from patients with immunodeficiency, centromeric instability, facial anomalies type I (ICF1) syndrome that harbor biallelic hypomorphic DNMT3B mutations." (PMID 38136588, 2023). "During development and cell proliferation, mutations in DNMT3B contributes to immunodeficiency–centromeric instability–facial anomalies syndrome (ICF syndrome), which is an immunodeficiency disease with the presence of centromeric instability and facial anomalies." (PMID 34281195, 2021). "Similarly, in the Immunodeficiency with Centromeric instability and Facial anomalies (ICF) syndrome, germ line mutations in DNMT3B lead to perturbed methylation patterns." (PMID 25198254, 2014). "Immunodeficiency, centromeric instability and facial anomalies (ICF) syndrome type I is a rare autosomal recessive disorder caused by mutations in DNA methyltransferase 3B (DNMT3B)." (PMID 23450006, 2013). "Immunodeficiency, Centromere instability, and Facial anomalies (ICF) syndrome which is caused by mutations in DNMT3b, is characterized by centromeric instability of chromosomes 1, 9 and 16, which is associated with abnormal hypomethylation of CpG sites within pericentromeric satellite regions." (PMID 19506729, 2008). "Our observations could also offer an explanation for the enigmatic de-repression of PRC2-target developmental genes in cells of patients with immunodeficiency-centromeric instability-facial abnormalities (ICF) syndrome, a disorder frequently caused by mutation in DNMT3B." (PMID 23531360, 2013). "In addition, biallelic DNMT3B mutations in Immunodeficiency, Centromeric instability, and Facial anomalies syndrome 1 (ICF1) patients, most of which are loss of function variants in the C-terminal catalytic domain of DNMT3B, are also associated with severe D4Z4 hypomethylation." (PMID 38809976, 2024). "Four patients had immunodeficiency with centromeric instability and facial anomalies (ICF) due to a mutation in either DNMT3B or ZBTB24, while two patients have no identifiable mutations in ICF-causing genes despite satisfying clinical, immunologic, and cytogenetic diagnostic criteria." (PMID 30697212, 2018).
hepatocellular carcinoma (43 papers, 2008 to 2026). A malignant tumor that arises from hepatocytes. "Similarly, the increased expression of DNMT3B is associated with sorafenib resistance in hepatocellular carcinoma cells, and inhibiting DNMT3B can increase their sensitivity to sorafenib." (PMID 38067304, 2023). "DNMT3B has been found to be highly correlated with the oncogenesis, growth, metastasis, or prognosis of cancers such as hepatocellular carcinoma, bladder cancer, and papillary thyroid cancer." (PMID 37686409, 2023). "The authors found that CD133 stabilized DNA methyltransferases (DNMT) activity via the regulation of DNA (cytosine-5)-methyltransferase 3 beta (DNMT3B) expression in several hepatocellular carcinoma cells." (PMID 37446085, 2023). "FOXC1 induced CTH promoter DNA hypermethylation through upregulation of DNMT3B to promote proliferation and metastasis in primary hepatocellular carcinoma." (PMID 34904288, 2022). "FOXC1 induces CTH promoter DNA hypermethylation through upregulation of DNMT3B to promote proliferation and metastasis in primary hepatocellular carcinoma." (PMID 34970791, 2022). "Survival analyses with the univariate Cox regression model revealed their crucial roles in the patient outcomes, of these, DNMT3A, UHRF1, DNMT1, DNMT3B and TET1 the risk factors for hepatocellular carcinoma." (PMID 35771147, 2022). "Compared to patients with higher expression of DNMT3B, patients with lower expression of DNMT3B had a better prognosis, which is consistent with previous research in hepatocellular carcinoma." (PMID 33221743, 2020). "DNMT3B is upregulated in various malignant tumors, such as lung cancer, hepatocellular carcinoma, prostate cancer, melanoma, and bladder cancer." (PMID 33221743, 2020). "In the same vein, silencing DNMT1 and DNMT3b in human hepatoma cells restores DR5 expression and TRAIL sensitivity." (PMID 31248188, 2019). "In the current study, we investigated the effects of 5-aza-2'-deoxycytidine alone and suppression of DNMT1 or DNMT3B on human hepatoma cell lines." (PMID 27994704, 2008). "In this study, we try to knock down the expression of DNMT1 or DNMT3B via siRNA to explore the mechanism of DNMTs involved in hepatoma therapy." (PMID 27994704, 2008). "Interestingly, the adapter molecule and potential tumor suppressor molecule Metastasis Suppressor 1 (MTSS1) has recently been described to be a transcriptional target of DNMT3B in hepatocellular cancer." (PMID 25996952, 2015). "One of the novel findings of our present study is that DNMT3B siRNA could induce more genes identical to demethylation agent in hepatocellular cancer." (PMID 27994704, 2008). "The TERT/SP1 interplay displays further complexity via evidence of co-activation roles on DNMT3B expression in hepatocellular carcinoma (HCC)." (PMID 33802026, 2021). "DNMT3B might be a new potential target for therapy of hepatocellular carcinoma." (PMID 27994704, 2008). "In hepatocellular carcinoma, lncRNA BZRAP1-AS1 promotes the malignant phenotype of HCC cells by interacting with DNMT3b to downregulate THBS188." (PMID 37781524, 2023). "More recently, IL-6/JAK1-mediated STAT3 phosphorylation was found to promote the transcription of DNMT3B and OCT4 in hepatocellular carcinoma cells, which can further up-regulate the transcription of DNMT156." (PMID 32895373, 2020). "It was shown, however, to be highly expressed in hepatocellular carcinoma and inhibited the transcription of THBS1 by recruiting DNMT3b to its promoter region." (PMID 33274204, 2020). "In this article, we aimed to explore the potential protective effect of curcumin against UV radiation-induced DNMT1, DNMT3A, DNMT3B, HDAC5, and HDAC6 expression in immortalized keratinocytes (HaCaT), hepatocellular carcinoma (HepG2), and lung adenocarcinoma (A549) cells." (PMID 41901340, 2026).
hepatocellular carcinoma (continued). "For example, Shehawy demonstrated that the strong interaction between the herbal active ingredients Thymoquinone and Piperine with DNMT3B and HDAC3 inhibited the activity of hepatocellular carcinoma cells and led to growth arrest and cell death by molecular docking." (PMID 40406241, 2025). "It has been reported that DNMT3B may play a critical role in the IL-6-mediated OCT4 expression and the drug sensitivity of sorafenib-resistant hepatocellular carcinoma." (PMID 37934565, 2023). "To date, except for MCL1 which has been proven by us and other literature studying hepatocellular carcinoma, among the validated miR-26a targets, HMGA1, PTEN, EZH2, MITF, DNMT3B, TGF-beta, and Ezh2 have been demonstrated to regulate chemoresistance." (PMID 33816494, 2021). "They found that TERT depletion in hepatocellular carcinoma cells (HCC) resulted in reduced DNMT3B transcription, and they proposed that TERT itself may cooperate with the transcription factor Sp1 to promote DNMT3B transcription." (PMID 32297856, 2020). "Moreover, either DNMT3A or DNMT3B is found in many clinical tumor samples, and the increased expression of DNMT3A was previously reported to participate in the progression of hepatocellular carcinoma." (PMID 31311130, 2019). "Similarly, in hepatocellular carcinomas, there is increased expression of DNMT1, DNMT3a, and DNMT3b and a progressive increase in the number of methylated genes from normal liver, chronic hepatitis/cirrhosis to hepatocellular carcinoma." (PMID 24822169, 2014). "Additionally, the FOXM1/RB1/DNMT3B transcriptional regulatory complex can suppress the expression of FOXO1, resulting in decreased levels of FOXO1 target p16, p21, and p27 in hepatocellular carcinoma (HCC)." (PMID 38672640, 2024). "In addition, significant overexpression of DNMT3b and reduced expression of DNMT2 were observed in hepatocellular carcinomas compared with the corresponding non-cancerous liver tissues." (PMID 24822169, 2014).